KRT7 (keratin 7)
Diseases named in the same sentence as KRT7 in open-access papers (continued):
Sharing a sentence is not in itself a finding about the gene and the disease.
lung carcinoma (81 papers, 2002 to 2025). "In addition, the aberrant expression of KRT7 in lung cancer cells could make it a potential diagnostic biomarker for the disease." (PMID 39329988, 2024). "Thyroid transcription factor-1 (TTF-1) and cytokeratin 7 (CK7) are markers used to diagnose the histological subtype of lung cancer and to distinguish primary LUAD." (PMID 40275403, 2025). "In lung cancer, the upregulation of KRT7 mRNA indicated the presence of CTCs among the peripheral blood cells." (PMID 39329988, 2024). "High levels of KRT7 would help identify the subtypes of lung cancer or predict patient prognosis, guiding personalized treatment strategies." (PMID 39329988, 2024). "High expression of Krt7 in carcinoma has been reported as an independent factor for poor prognosis of multiple types of cancer, including breast, colorectal, prostate, and lung cancers." (PMID 38059647, 2024). "Regarding morphology, tumors in our model appeared to be papillary carcinomas, all TTF-1 and cytokeratin-7 positive analogous to human lung cancers." (PMID 29415661, 2018). "Immunohistochemical staining for thyroid transcription factor-1 and cytokeratin 7 confirmed that the two resected tumors were metachronous metastases of the primary lung cancer." (PMID 25889744, 2015). "Epithelial cells were further characterized by highlighting positivity for tissue-specific cytokeratins, such as cytokeratin-19 for breast and thyroid carcinomas and cytokeratin 7 for lung carcinomas." (PMID 24098684, 2013). "Adenosquamous carcinoma (ASC) is an aggressive type of lung cancer that contains a mixture of cells with squamous (cytokeratin 5+) and adenocarcinoma (cytokeratin 7+) phenotypes." (PMID 24324581, 2013). "In AC, we found an up-regulation of keratin 7, a characteristic finding for pathologists to diagnose this subtype of lung cancer." (PMID 18992152, 2008). "The immunostaining for KRT7 of tumors and CTCs may help diagnose lung cancer and optimize the treatment strategy for individual patients." (PMID 39329988, 2024). "In addition, the CST6-related genes (ITGA3, LKL7, and KRT7 corresponding to TCGA lung cancer, SKCM, and renal cancer separately) were found to be associated with clinical outcomes." (PMID 34603393, 2021). "Wedge resections through video assisted thoracic surgery were performed and one of them underwent lobectomy and mediastinal lymph node dissection after the primary lung carcinoma being proved pathologically (thyroid transcription factor 1 and cytokeratin 7 positive)." (PMID 19830039, 2009). "Also known as cytokeratin-7 (CK7), KRT7 expression in lung cancer is associated with lymph node metastasis and T stage, which may serve as an independent factor for poor prognosis of lung cancer." (PMID 37920509, 2023). "However, HE staining and immunostaining for alpha smooth muscle actin (αSMA) and Cytokeratin 7 (CK7) demonstrated that only the OSK-A549-Colony cells could form cohesive cell nests that were similar to human lung cancer tissues, and we called these nests “lung cancer organoids”." (PMID 28951614, 2017). "The most useful immunohistochemical stains to differentiate gastrointestinal carcinoma from lung carcinoma are TTF-1, cytokeratin 7, cytokeratin 20, CDX2, and villin." (PMID 23119210, 2012). "The most common immunostains used in lung cancer BM workups are TTF-1, cytokeratin 7 (CK7) and p63." (PMID 39570822, 2024). "Some of these genes have been well characterized in lung cancer, for instance, NAPSA29 is a common prognostic marker for LUAD, and KRT18, KRT7, and GPRC5A have been reported to play important roles in tumor progression and chemoresistance in various types of cancers." (PMID 35102706, 2022). "However, they did not suggest using KRT7 mRNA for monitoring the therapeutic response to the chemotherapeutic drugs or survival rate in patients with advanced lung cancer because CTCs appeared to be significantly more resistant to chemotherapeutic drugs than non-metastatic tumor cells." (PMID 39329988, 2024).
lung carcinoma (continued). "Positive IHC staining for thyroid transcription factor 1 and cytokeratin-7 and negative staining for CK20 and CDX2 strongly correlate with GI metastases from lung cancer." (PMID 38957515, 2024). "Interestingly, the expression of TTF-1 and cytokeratin 7 (CK7), which is found in simple epithelia in several organs, has been positively correlated with Enterobacteriacee presence in a context of dysbiosis of the salivary microbiome of non-smoking female lung cancer patients." (PMID 35804901, 2022).
squamous cell carcinoma (54 papers, 2009 to 2026). A carcinoma arising from squamous epithelial cells. "KRT7 is highly expressed in 90%–95% of LUADs but is absent in squamous cell carcinoma, which could be used as a diagnostic differentiation." (PMID 41488744, 2026). "Tumors with poorly defined transition areas between healthy skin and tumor cells, corresponding by extrapolation to the field cancerization of squamous cell carcinoma/actinic keratoses, often require specific immunohistochemistry studies (S-100, Sox-100, PRAME) in melanoma and cytokeratin 7 in EMPD." (PMID 39797152, 2024). "A previous study showed high expression levels of KRT7 and KRT19 in Cervical Intraepitelial Neoplasm grade 3 (CIN3) and squamous cell carcinoma (SCC), supporting the idea that KRT19 may promote E7 oncoprotein production, contributing carcinogenic events." (PMID 32337254, 2020).
colon carcinoma (48 papers, 1994 to 2026). "In one of our previous studies, based on an investigation of 52 cases, we proved that Cytokeratin 7 (CK7) was positive in the MSI right-sided BRAF-mutated colon carcinomas, which, probably, were serrated adenocarcinomas." (PMID 23469219, 2013). "KRT7, a membrane-cytoskeleton linker required for cell adhesion, is overexpressed in colon cancer and esophageal squamous cell carcinoma, and is associated with poor survival and metastasis in colon cancer." (PMID 32081836, 2020). "It stained positive for cytokeratin 20, CDX2, and CEA, as colonic cancers do, but was also immunoreactive for cytokeratin 7 and p16, which are characteristic for the female genital tract neoplasms." (PMID 24307962, 2013). "Evidence for KRT7 in resistance specifically against anti-metabolites was shown by cellular response to 5-fluorouracil in 5-FU-resistant colon cancer cell lines during treatment and recovery where KRT7 was among the differentially overexpressed genes." (PMID 22905093, 2012). "Keratin 7 seems to be involved in metastasis in colon carcinoma." (PMID 30001402, 2018). "Primary colon cancer is usually cytokeratin-7 negative and cytokeratin-20 positive, whereas endometrial cancers are usually cytokeratin-7 positive and cytokeratin-20 negative, and urothelial cancers are often positive for GATA-3." (PMID 40678160, 2025). "Interestingly, cytokeratin 7—a keratin not normally expressed in adult intestinal epithelium, but a component of the foetal gene program—is strongly expressed in BA colonic tumour epithelium." (PMID 34103493, 2021). "Interestingly, all adenocarcinomas including anastomotic site tumors were positive for cytokeratin 7 but negative for cytokeratin 20 and β-catenin nuclear accumulation, which is uncommon for colon cancers." (PMID 26649222, 2015). "Immunohistochemically, tumor cells from the ovaries and the colon both showed positive expression of cytokeratin 20 (CK20) but no expression of cytokeratin 7 (CK7), confirming that the ovarian tumors were metastases from primary colon cancer." (PMID 27842595, 2016).
ovarian carcinoma (48 papers, 1994 to 2025). A malignant neoplasm originating from the surface ovarian epithelium. "It was observed in a recent publication that KRT7 overexpression in ovarian cancer cell lines was associated with increased proliferation, migration and EMT marker expression through the regulation of the TGF-β/Smad2/3." (PMID 34070214, 2021). "In ovarian cancer cells, KRT7 overexpression was associated with increased proliferation, migration and EMT." (PMID 35011679, 2021). "In ovarian cancer, KRT7 overexpression was associated with EMT." (PMID 37954148, 2023). "Among these, PAX8 expression was high in ovarian cancer cell lines, whereas cytokeratin 7 expression was high in IHOSE cell lines." (PMID 40034272, 2025). "KRT7 regulates EMT in ovarian cancer via the TGF-ß/Smad2/3 pathway, and regulates cell-matrix adhesion through integrin-ß1-focal adhesion kinase signaling." (PMID 37954148, 2023). "In ovarian cancer, KRT7 overexpression was associated with increased proliferation, migration and EMT of ovarian cancer cells." (PMID 37954148, 2023). "Immunocytochemistry analysis of anti-cytokeratin 7 staining revealed an average of ~ 90% ovarian cancer cell purity within the isolated cell populations." (PMID 35672728, 2022). "Immunocytochemistry analysis of anti-cytokeratin 7 staining revealed the more than 90% purity of ovarian cancer cell within the isolated cell populations." (PMID 34539881, 2021). "In ovarian cancer cell line SKOV3, KRT5 and KRT7 were upregulated by Forkhead box M1 (FOXM1) and KRT5 and KRT7 deficiency prevented migration." (PMID 34070214, 2021). "The carcinomas in SCID pigs were morphologically similar to the original ovarian carcinoma and had the same immunohistochemical phenotype based on expression of Claudin 3, Claudin 4, Cytokeratin 7, p16, and EMA." (PMID 30723704, 2019). "Immunocytochemistry analysis of anti-cytokeratin 7 staining revealed an average of approximately 84.61 % ovarian cancer cell purity within the isolated cell populations." (PMID 27012847, 2016). "These primary ovarian cancer cells were further identified by immunocytochemistry assay with anti-cytokeratin 7 staining." (PMID 23593287, 2013). "Primary peritoneal cystadenocarcinoma and primary ovarian carcinoma both stain positive for estrogen receptor (ER), cytokeratin 7 (CK7), Wilm's tumor suppressor gene (WT1), and cancer antigen 125 (CA 125)." (PMID 18036260, 2007). "Recent studies have demonstrated that immunostaining for KRT7 and 20 can effectively differentiate primary ovarian carcinomas from metastatic carcinomas originating from the gastrointestinal tract and pancreas, which clinically resemble primary ovarian carcinoma." (PMID 38260844, 2023). "KRT7 was also reported to promote epithelial-mesenchymal transition (EMT) of ovarian cancer." (PMID 34422643, 2021). "Markers such as Cytokeratin 7, PAX8, and E-cadherin provide critical insights into various aspects of ovarian cancer research." (PMID 40034272, 2025). "Genes that contributed to the most variation between subtypes included known biomarkers and master regulators of ovarian cancer subtypes (MUC16 and PAX8) and many keratin and cadherin genes (KRT19, KRT7, KRT8, CDH6, and CDH1)." (PMID 39131380, 2024). "For instance, they have been utilized in the differentiation of mCRC (metastatic colorectal carcinoma), which is KRT20-positive and KRT7-negative, from primary ovarian carcinoma, which is KRT20-negative and KRT7-positive." (PMID 38260844, 2023). "have shown that the TGF-β/Smad2/3 pathway, which is activated by KRT7, represents the primary pathway responsible for inducing EMT in ovarian cancer." (PMID 38260844, 2023). "Keratin 7, a molecule of the keratin family, has been characterized to drive EMT of ovarian cancer cells through the TGF-β/SMAD2/3 pathway." (PMID 36248424, 2022).
ovarian carcinoma (continued). "1, 2, 4, 12 and 14) further confirmed the tumor origin by cell surface staining of the ovarian cancer marker CA125 and the epithelial cell marker epithelial cell adhesion molecule (EpCAM), and intracellular staining of cytokeratin 7 (CK7)." (PMID 33346216, 2020). "Cytokeratin 7 (CK7) and paired box gene 8 (PAX8) are currently the best markers for determining primary origin in ovarian carcinoma, stomach cancer, and pancreatobiliary tract cancer." (PMID 30024911, 2018). "KRT5 has been shown to inhibit melanoma metastasis 21, while studies have suggested that a lack of KRT5 and KRT7 can impede ovarian cancer cell migration." (PMID 38495507, 2024). "A recent study on the origin of ovarian cancer connected fallopian tube epithelial cell subtypes to intra-tumor heterogeneity in serous ovarian cancer (SOC), and used KRT7 as a marker for secretory epithelial (SE) cells in the fallopian tube as the cell-of-origin for SOC." (PMID 38328306, 2023). "Immunohistochemical staining of vimentin (VIM), CD45, and cytokeratin-7 (CK7) was also performed on tumor tissues from metastatic and primary tumors belonging to different ovarian cancer histotypes to investigate the fractions of the major cell lineages in these tumors." (PMID 38328306, 2023). "Ovarian cancer cells are KRT7+/KRT20−, whereas prostate cancer cells are negative for both KRT7 and KRT20." (PMID 35267493, 2022).
colorectal adenocarcinoma (45 papers, 2002 to 2025). The most common type of colorectal carcinoma. "In terms of immunohistochemical profile, KRT7 expression was more prominent in micropapillary colorectal carcinomas (17%) than in conventional colorectal adenocarcinomas (3%)." (PMID 38260844, 2023). "Most colorectal adenocarcinomas are cytokeratin 7−/cytokeratin 20+, whereas most ovarian mucinous cancers are cytokeratin 7+/cytokeratin 20+, as seen in our case." (PMID 25821618, 2015). "Expression of cytokeratin 7 (CK7) is established in most malignancies including gastric and colorectal adenocarcinoma." (PMID 26644898, 2015). "Out of the 102 samples, in 95% (97 out of 102) of the cases, the cytokeratin 7 and cytokeratin 20 staining pattern characterised and differentiated between lung and colorectal adenocarcinoma." (PMID 12085180, 2002). "Primary and metastatic lung adenocarcinomas show a cytokeratin 7+/cytokeratin 20− staining pattern, while colorectal adenocarcinomas stain cytokeratin 7−/cytokeratin 20+." (PMID 12085180, 2002). "In contrast, typical colorectal adenocarcinomas are usually positive for CDX2 and CK20, and negative for cytokeratin 7 (CK7), supporting a non-colorectal origin in this case." (PMID 40662033, 2025).
gastric cancer (44 papers, 2008 to 2026). A primary or metastatic malignant neoplasm involving the stomach. "This last observation corroborates results from a recent publication where KRT7 overexpression was associated with poor prognosis in gastric cancer patients." (PMID 34070214, 2021). "In esophageal squamous cell and in gastric carcinoma, where KRT7 overexpression is associated with a poor prognosis, KRT7 was transcriptionally upregulated by FOXA1." (PMID 34070214, 2021). "Immunohistochemical analysis of this tissue revealed cytokeratin 7 positivity and cytokeratin 20 negativity, identical to the gastric carcinoma resected 29 years earlier." (PMID 42186636, 2026). "Our analysis of KRT7 in publicly available cancer databases has highlighted that KRT7 gene expression is a prognostic marker of poor outcome in several cancer types including breast, non-small-cell lung, and gastric carcinomas." (PMID 34070214, 2021). "Moreover, in pancreatic cancer and gastric cancers, heightened KRT7 expression correlates with poor prognoses." (PMID 39095562, 2024). "The organoids faithfully recapitulated important characteristics of the corresponding parent tumors as exemplified by architectures, the expression of typical gastric cancer markers including carcinoembryonal antigen, cadherin 17, cytokeratin 7 (KRT7), and periodic acid Schiff reaction." (PMID 30219074, 2018). "The combination of cytokeratin 7 and cytokeratin 20 has been widely employed to distinguish among different types of carcinoma and it may be useful in distinguishing mammary from gastric carcinoma." (PMID 25400965, 2014). "Immunohistochemistry was negative for PSA and NKX3.1, but positive for cytokeratin 7, and histological comparison with the prior gastric specimen confirmed metastatic gastric cancer to the prostate." (PMID 40821321, 2025). "Five genes, e.g., DGAT2, JAKMIP1, KRT7, PGLYRP1, and TINAGL1, showed very low correlation coefficient and/or insignificant p-values, suggesting they might not be regulated by KLF5 in human gastric cancer." (PMID 33923166, 2021).